ZBBX (zinc finger B-box domain containing)
Synonyms: FLJ23049
Tractability: No criterion of Open Targets' tractability assessment is met for any kind of drug.
Gene: Protein-coding gene on chromosome 3 (167,239,843 to 167,407,874, reverse strand). Ensembl gene ENSG00000169064.
Subcellular location (Human Protein Atlas): Golgi apparatus
Genetic constraint (gnomAD): Loss-of-function variants: 48 observed, 53.22 expected, observed/expected ratio (o/e) 0.9, 90% interval 0.71 to 1.15. The upper end of that interval is the gene's LOEUF score, 1.15, which puts it in group 5 of 6, group 1 being the genes least tolerant of losing a copy. Missense variants: 670 observed, 625.61 expected, observed/expected ratio (o/e) 1.07, 90% interval 1 to 1.14. Synonymous variants: 241 observed, 223.08 expected, observed/expected ratio (o/e) 1.08, 90% interval 0.97 to 1.2.
Homologues: Orthologues: chimpanzee ZBBX (98% identical), macaque ZBBX (92% identical), dog ZBBX (74% identical), pig ZBBX (72% identical), rabbit ZBBX (72% identical), rat Zbbx (54% identical), mouse Zbbx (48% identical).
Diseases named in the same sentence as ZBBX in open-access papers:
ZBBX is named in the same sentence as 2 diseases in open-access papers, as found by Europe PMC text mining. Sharing a sentence is not in itself a finding about the gene and the disease. The quoted sentences say what the papers report.
Alzheimer disease (1 paper, 2021). A progressive, neurodegenerative disease characterized by loss of function and death of nerve cells in several areas of the brain leading to loss of cognitive function such as memory and language. "In the case of ZBBX, this gene does not map to any known pathways and we could not find evidence in the scientific literature of links with Alzheimer’s disease." (PMID 33411734, 2021).
ZBBX also shares sentences with these, for which no sentence is quoted: copy number variation (1 paper).